TRPM8 (transient receptor potential cation channel subfamily M member 8)
Diseases named in the same sentence as TRPM8 in open-access papers (continued):
Sharing a sentence is not in itself a finding about the gene and the disease.
esophageal cancer (continued). "Furthermore, TRPM8 inhibition aggravated cytotoxic ability of CD8+ T cells to esophageal cancer cells partially because of the decreased expression of PD-L1." (PMID 31519770, 2019). "In parallel, TRPM8 was up-regulated in esophageal cancer cell lines." (PMID 31519770, 2019). "Finally, we proved that TRPM8 regulated PD-L1 expression by calcineurin-NFATc3 pathway in esophageal cancer cells." (PMID 31519770, 2019). "In addition, TRPM8 antagonist resulted in a significantly higher apoptotic rate in esophageal cancer cells." (PMID 31519770, 2019). "Our study uncovered the pro-tumor role of TRPM8 in esophageal cancer." (PMID 31519770, 2019). "TRPM8 was up-regulated in esophageal cancer tissues and cell lines." (PMID 31519770, 2019). "Therefore, TRPM8 contributed to growth and immune evasion of esophageal cancer cells." (PMID 31519770, 2019). "The link between the pathophysiology of esophageal cancer and TRP channel expression has been exclusively made for ESCC and includes dysregulation of TRPC6, TRPM7, TRPM8, TRPV1, TRPV2, and TRPV4 expression levels." (PMID 32182937, 2020). "However, it is still unclear whether TRPM8 has biological effect on esophageal cancer." (PMID 31519770, 2019). "Finally, we explored the mechanism and found that calcineurin-nuclear factor of activated T cells 3 (NFATc3) pathway contributed to the expression of programmed death ligand 1 (PD-L1) induced by TRPM8 overexpression and TRPM8 agonist, which might lead to immune evasion of esophageal cancer cells." (PMID 31519770, 2019).
Pruritus (8 papers, 2017 to 2025). Pruritus is an itch or a sensation that makes a person want to scratch. "TRPM8 agonists such as cryosim-1, menthoxypropanediol, and icilin can significantly improve recalcitrant pruritus associated with many diseases, including eczema, urticaria, AD, lichen sclerosus et atrophicus, and scalp itch." (PMID 37555911, 2023). "Activation of TRPM8 induces a long-lasting cooling effect in the skin, and the application of cold is a well-known remedy for pruritus in many conditions." (PMID 37555911, 2023). "Cryosim-1, a topical synthetic TRPM8 agonist, has been evaluated in randomized controlled trials for the treatment of pruritus." (PMID 36613861, 2022). "Icilin, a potent TRPM8 activator, is effective in reducing vulva pruritus resulting from lichen sclerosus et atrophicus." (PMID 30301231, 2018). "Menthol and its analogs that rely on TRPM8 channels are a promising target for the development of pruritus therapies, and further clinical trials could significantly improve the management of pruritus." (PMID 36277488, 2022). "Therefore, further studies should be conducted to evaluate topical TRPM8 agonists in the treatment of certain types of pruritus, as it could aggravate itch in some conditions such as psoriasis." (PMID 36613861, 2022). "In this review, we discuss the role of TRP channels TRPA1, TRPV1, TRPV2, TRPV3, TRPV4, TRPM8, and TRPC3/4 in acute and chronic pruritus." (PMID 38139833, 2023). "Generally, TRPM8 activity inhibits pruritus rather than inducing it, unlike other TRP channels." (PMID 39771213, 2024). "Therefore, despite not being pruriceptors, TRPM8 neurons are important in suppressing pruritus, as they are part of a spinal interneuron circuit that includes B5-I neurons." (PMID 39771213, 2024).
painful bladder syndrome (7 papers, 2006 to 2022). "TRPM8 seems overexpressed in patients with painful bladder syndrome and idiopathic detrusor overactivity, where the levels of TRPM8 appear to correlate with the perceived pain and frequency of micturition." (PMID 35976012, 2022). "The increased expression levels of TRPM8 mRNA have been found in interstitial cystitis/bladder pain syndrome (IC/BPS)." (PMID 34445208, 2021). "In this study, we report the distribution of the cool and menthol receptor TRPM8 in the urinary bladder in patients with overactive and painful bladder syndromes, and its relationship with clinical symptoms." (PMID 16519806, 2006). "In a recent study, we demonstrated an increased expression of TRPM8 in suburothelial nerve fibres of patients with painful bladder syndrome (PBS) and idiopathic detrusor overactivity (IDO)." (PMID 17192176, 2006). "This study shows a significant increase of TRPM8-immunoreactive nerve fibres in suburothelium from patients with overactive and painful bladder syndrome." (PMID 16519806, 2006). "A recent study, for example, suggests that inhibition of TRPM8 could be useful in overactive bladder and painful bladder syndromes treatment." (PMID 24288041, 2011). "Notably, expression of TRPM8 is markedly augmented in bladder specimens from patients with idiopathic detrusor overactivity and painful bladder syndrome." (PMID 24288041, 2011). "To further our understanding of role of TRPM8 in the pathophysiology of bladder dysfunction, and discover any relationship with clinical symptoms, we have studied the expression of TRPM8 receptors in overactive and painful bladder syndromes." (PMID 16519806, 2006). "The number of TRPM8-immunoreactive suburothelial nerves is increased in patients with idiopathic detrusor overactivity, and the relative density of TRPM8-immunoreactive nerve fibers significantly correlates with symptoms of overactive bladder and painful bladder syndrome." (PMID 27713353, 2010). "Previous studies have shown a positive correlation between TRPM8 expression and voiding frequency in patients with bladder conditions, such as OAB symptoms and painful bladder syndrome (PBS) patients and an involvement of this channel on micturition reflex and nociceptive signalling." (PMID 24593692, 2014). "We have recently shown an increase of nerve fibres expressing the cool and menthol receptor TRPM8 in both overactive (IDO) and painful bladder syndrome (PBS), but its functional significance is unknown." (PMID 17192176, 2006).
retinoblastoma (7 papers, 2013 to 2025). A malignant tumor that originates in the nuclear layer of the retina. "TRPV1, TRPM8 and TRPA1 are expressed in retinal tumour cells (retinoblastoma)." (PMID 26605361, 2015). "Another study revealed TRPV1, TRPM8 and TRPA1 gene expression in retinoblastoma cells." (PMID 26605361, 2015).
bladder cancer (6 papers, 2017 to 2024). "For example, the cell death induction in human bladder cancer T24 cells has associated with TRPM8, which occurs by menthol increased the concentration of intracellular calcium and induced mitochondrial membrane depolarization through TRPM8 channels." (PMID 36923503, 2023). "Some reports demonstrated that TRPM8 is significantly overexpressed in the cell membrane and cytoplasm of human bladder cancer cells." (PMID 37033630, 2023). "In bladder cancer, TRMP8 also regulates ROS production and the expression levels of the enzymes Catalase, HO-1, and SOD2, which regulate tumor growth in vivo, demonstrating that TRPM8 has an essential role in bladder cancer." (PMID 37033630, 2023). "Menthol increases mitochondrial membrane depolarization through TRPM8 channel leading to cell death in human bladder cancer T24 cells and enhances anti-tumor effects by downregulating cytochrome P450 3A4 (CYP3A4) in human hepatocellular carcinoma HepG2 cells." (PMID 36923503, 2023). "Knockdown of TRPM8 in bladder cancer cells decreases p-AKT and increases p-GSK-3β level, which alters the process regulated by the AKT/GSK-3β signaling." (PMID 37033630, 2023). "Knockdown of TRPM8 attenuates bladder cancer proliferation and progression in T24 cells and slows down tumour growth and progression in a murine model of human urinary bladder cancer." (PMID 33430230, 2021). "In case of bladder cancer, TRPM8 expression is increased in cancerous tissue." (PMID 39150496, 2024). "In T24 human bladder cancer cells, menthol increases the intracellular Ca2+ concentration, mitochondrial membrane depolarization, and cell death in a dose-dependent way, suggesting the potential use of TRPM8 agonists in the cancer cell." (PMID 37033630, 2023). "However, a considerable reduction in the expression level of TRPM8 mRNA was also reported in bladder cancer tissues." (PMID 37033630, 2023). "Recent scientific attention was given to TRPM8 in bladder cancer metastasis." (PMID 33430230, 2021).
Pain (6 papers, 2017 to 2025). An unpleasant sensory and emotional experience associated with actual or potential tissue damage, or described in terms of such damage. "This study unveils the central role of TRPM8 and Kv1 channels in damage-triggered cold allodynia in orofacial neuropathic pain." (PMID 39703391, 2024). "Much like in animal models of neuropathic pain, animal models of bladder pain reveal TRPM8 to be pro-nociceptive." (PMID 28358322, 2017). "Two case studies also demonstrate the analgesic role of TRPM8 in patients suffering from chronic neuropathic pain." (PMID 28358322, 2017). "Moreover, IGM-18 exerted an analgesic effect on formalin-induced orofacial pain and chronic constriction injury-induced neuropathic pain, demonstrating the involvement of TRPM8 channels in these two pain models." (PMID 31703254, 2019). "Our results are the first to demonstrate that such an outcome may be obtainable via cooling-induced uptake in TRPM8+ nerve fibers in the treatment of inflammatory and neuropathic pain." (PMID 30271936, 2018). "Further, the research findings indicate that sodium, potassium, and calcium ion channels, in conjunction with diverse transient receptor potential families (e.g., TRPA1, TRPM8, and TRPV1), play a pivotal role in the pathophysiology of oxaliplatin-induced neuropathic pain." (PMID 40649805, 2025).
chronic obstructive pulmonary disease (5 papers, 2017 to 2024). A chronic and progressive lung disorder characterized by the loss of elasticity of the bronchial tree and the air sacs, destruction of the air sacs wall, thickening of the bronchial wall, and mucous accumulation in the bronchial tree. "Interestingly, three single nucleotide polymorphisms (SNPs) in the TRPM8 gene (rs9789675, rs9789398, and rs1004478) are significantly associated with the risk of PH in Han Chinese patients with chronic obstructive pulmonary disease (COPD)." (PMID 30322215, 2018). "Also, variants in CAV1, TRPM8, and BNP have been linked with PH secondary to chronic obstructive pulmonary disease." (PMID 33996849, 2021). "Certain transient receptor potential (TRP) channels including TRPM8 and TRPA1 are widely expressed in the respiratory tract and have been shown to be the receptors of cigarette smoke and particulate matter—the main causative factors of chronic obstructive pulmonary disease (COPD)." (PMID 33567636, 2021). "We extend the characterization of the TRPM8 antagonist VBJ103 with tests of selectivity, specificity and distribution, therapeutic efficacy of systemic administration against oxaliplatin-induced cold hyperalgesia and the impact of systemic administration on core body temperature (CBT)." (PMID 38794851, 2024).
epilepsy (5 papers, 2019 to 2026). A brain disorder characterized by episodes of abnormally increased neuronal discharge resulting in transient episodes of sensory or motor neurological dysfunction, or psychic dysfunction. "Building on this mechanistic foundation, we investigated the temporal expression patterns of TRPM8 and its associated signaling molecules in a mouse model of epilepsy." (PMID 41474182, 2026). "Our present data showed that EDs were suppressed by TRPM8 agonist administration after epilepsy-inducer injection." (PMID 34658898, 2021). "Mice were injected with TRPM8 agonist 90 min after or 30 min before epilepsy-inducer injection, and electrocorticograms (ECoGs) were recorded under anesthesia, while behavior was monitored when awake." (PMID 34658898, 2021). "To clarify the effects of TRPM8 channel absence on PG-induced epilepsy, we recorded ECoGs in TRPM8KO mice." (PMID 34658898, 2021). "In addition, ED development and epileptic seizures were suppressed by TRPM8 agonist administration before the epilepsy-inducer injection." (PMID 34658898, 2021). "Our results suggest that TRPM8 activation in epileptic brain regions may be a new therapeutic approach for patients with epilepsy." (PMID 31263415, 2019). "In conclusion, the role of TRPM8 activation by icilin in suppressing EDs may be the basis for developing new drug treatment for patients with epilepsy." (PMID 31263415, 2019). "In addition, the lack of TRPM8 channels resulted in a shorter firing latency of EDs by the epilepsy inducer compared with that in WT mice (p < 0.001, p < 0.001, respectively, Welch’s t-test)." (PMID 34658898, 2021). "This deterioration in epilepsy resulting from a lack of TRPM8 channels may be due to the regulation of excitatory cells by TRPM8 activation." (PMID 34658898, 2021).
Headache (5 papers, 2012 to 2022). Cephalgia, or pain sensed in various parts of the head, not confined to the area of distribution of any nerve. "Ultimately, the context of when channel activation occurs may be relevant; if TRPM8 is activated alone it may cause headache as in the case of “ice cream headaches” while if it is activated along with ongoing inflammation, it may serve as an analgesic mechanism as is the case for topical menthol." (PMID 30970581, 2019). "Similarly, activation of meningeal TRPM8 channels in rats causes cutaneous facial and hindpaw allodynia, suggesting that preferential activation of dural TRPM8 channels/fibers may encode headache." (PMID 26111800, 2015). "In a rat behavioral model of headache, the TRPM8 agonist icilin applied onto the cranial dura mater was shown to produce cutaneous facial and hind paw allodynia that was attenuated by systemic pretreatment with a TRPM8 antagonist." (PMID 32088764, 2020). "Consistent with this idea is a recent publication demonstrating that when TRPM8 is activated in the presence of an ongoing inflammatory state induced by a cocktail of inflammatory mediators, the effect was a reduction in headache-related behavior." (PMID 30970581, 2019). "There have been conflicting reports as to what behavioral consequences are present when TRPM8 is activated in the meninges since studies have shown both increases and decreases in headache behavior in rodents following dural application of agonists." (PMID 30970581, 2019). "Thus, it seems that TRPM8 activation by exogenous agonists can both aggravate and alleviate headache-related behaviors, possibly depending on stimulation of other pro-nociceptive receptors of meningeal afferents." (PMID 32088764, 2020). "Taken together, our results suggest that TRPV1 and TRPA1 but not TRPM8 channels likely contribute to the excitation of dural afferent neurons and the subsequent activation of the headache circuit." (PMID 22971321, 2012). "However, it is not clear whether TRPM8-expressing dural afferent fibers may also exert anti-nociceptive function in the setting of meningeal irritation, which may occur during episodes of migraine headache." (PMID 26111800, 2015).
benign prostate hyperplasia (4 papers, 2016 to 2022). "Indeed, TRPM8 channel expression changes during PCa progression, revealing an upregulation in the early stages of both benign prostate hyperplasia and malignant prostate carcinoma followed by downregulation and silencing during late metastatic stages of PCa after hormonal therapy against androgens." (PMID 35743115, 2022). "Indeed, to support this hypothesis, a preclinical assay with a TRPM8 agonist (D-3263) show that TRPM8 activation decrease mice prostate hyperplasia." (PMID 27409624, 2016).
gastric cancer (4 papers, 2019 to 2024). A primary or metastatic malignant neoplasm involving the stomach. "Through clinical assessments, researchers observed significantly elevated levels of TRPM8 protein expression in gastric cancer tissues compared to adjacent healthy tissues." (PMID 39062591, 2024). "This identifies TRPM8 as a potential novel biomarker for gastric cancer diagnosis and treatment guidance, while also unveiling its potential as a therapeutic target." (PMID 39062591, 2024). "The presence of TRPM8 in patients with metastasis markedly exceeded that in individuals without metastasis, suggesting its potential role in promoting gastric cancer cell proliferation and metastasis." (PMID 39062591, 2024).
hepatocellular carcinoma (4 papers, 2024 to 2025). A malignant tumor that arises from hepatocytes. "Specifically, TRPM7 contributes to metabolic reprogramming in bladder, ovarian cancer and hepatocellular carcinoma and TRPM8 in hepatocellular carcinoma." (PMID 40813985, 2025). "Researchers initially identified the upregulation of TRPM8 expression in hepatocellular carcinoma, correlating with unfavorable pathological attributes." (PMID 39062591, 2024). "This regulatory mechanism may underpin TRPM8’s dual function in both promoting hepatocellular carcinoma cell proliferation and fostering liver regeneration." (PMID 39062591, 2024). "Inhibiting TRPM8 proves effective in curtailing hepatocellular carcinoma development." (PMID 39062591, 2024). "TRPM8 similarly supports tumor growth by modulating nuclear-mitochondrial communication; it induces SNORA55 expression, promoting mitochondrial biogenesis and hepatocellular carcinoma proliferation." (PMID 40813985, 2025).
injury (4 papers, 2009 to 2015). Damage inflicted on the body as the direct or indirect result of an external force, with or without disruption of structural continuity. "Our results show that upregulation of TRPM8 protein corresponds well with the induction and maintenance of sensitized pain responses of ipsilateral hind paw caused by nerve injury." (PMID 22111979, 2011). "In previous studies, much attention has been focused on the role of TRPM8 in the formation of cold hyperalgesia caused by nerve injury." (PMID 22111979, 2011). "This is consistent with previous studies indicating that cutaneous TRPM8 channels mediate cooling-induced analgesia in the setting of tissue- and nerve injury-induced chronic pain." (PMID 26111800, 2015). "TRPM8 may play different roles in mechanical allodynia, cold and thermal hyperalgesia that develop after nerve injury, and it is a very promising research direction for the development of new therapies for chronic neuroapthic pain." (PMID 22111979, 2011). "Previous studies have demonstrated important roles for TRPV1, TRPM8, and TRPA1 in inflammation and nerve injury induced pain." (PMID 20205720, 2010). "In contrast, another study suggested that neither TRPM8 nor TRPA1 was likely to contribute directly to cold hyperalgesia in rats with nerve injury." (PMID 22111979, 2011).
irritable bowel syndrome (4 papers, 2019 to 2023). Irritable bowel syndrome (IBS) is a chronic functional condition of the lower gastrointestinal (GI) tract characterized by abdominal pain or discomfort and disordered bowel habit (diarrhea, constipation, or fluctuation between the two). "In the context of complicated TRP channel interactions, menthol, as a natural agonist of TRPM8, may act similarly to icilin, also playing a pro-and anti-nociceptive role in irritable bowel syndrome." (PMID 36439160, 2022).